CASP8 (caspase 8)
Diseases named in the same sentence as CASP8 in open-access papers (continued):
Sharing a sentence is not in itself a finding about the gene and the disease.
cancer (continued). "Downregulation of Casp8 in both the cancer cells and/or NK cells may lead to severe immune tolerance because of the upregulation of PD‐L1 and/or PD‐1 and CTLA‐4." (PMID 33934451, 2021). "Since radiation also induced apoptosis in caspase-8 cancer cells, tested whether caspase-3 remains activated in those cells." (PMID 34710995, 2021). "Administration of Res sensitizes cancer cells to apoptosis via NF-κB down-regulation leading to a decrease in the level of anti-apoptotic factor Bcl-2 and an increase in apoptotic factors caspase-3 and caspase-8." (PMID 33478512, 2021). "Therefore, drug-induced caspase-8 expression is a promising therapeutic opportunity in cancers with low Caspase-8 levels." (PMID 33026575, 2021). "NF-κB activation was proposed as a pro-survival alternative function of caspase-8 in cancer." (PMID 34482382, 2021). "Based on these results, we speculate that ripoptosome, a cytoplasmic complex consisting of RIP1, FADD, and caspase 8, plays a crucial role in the cell death signaling upon treatment with the anti-cancer drugs." (PMID 33800107, 2021). "As a regulator of the homeostasis of adipocytes, caspase-8 might be therefore a possible target for new cancer therapies." (PMID 33026575, 2021). "It was more likely that c-Src–caspase-8 interaction had a key role in human cancers." (PMID 34367939, 2021). "Caspase 8 is a protein involved in the process of cell apoptosis, which may affect the efficacy of anti-cancer treatment." (PMID 33800294, 2021). "In addition, other studies have also found that ursolic acid downregulated the expression of Bcl-2 by activating caspase-3, caspase-8, and caspase-9, thereby inhibiting the proliferation of cancer cells and inducing apoptosis." (PMID 34194533, 2021). "CASP8 mediates apoptosis, and increased expression is observed in many cancer types." (PMID 34206510, 2021). "In summary, our data indicated that cancer patients with low Casp8 expression might benefit the most from anti‐PD‐1 or anti‐CTLA‐4 immunotherapy." (PMID 33934451, 2021). "However, the significance of these mechanisms to regulate caspase-8 in cancers has to be further investigated." (PMID 33026575, 2021). "Carrageenan mechanism in inhibiting the growth of cancer cells has also been investigated, where carrageenan is able to induce the process of apoptosis through activating the pathways of caspase-3, caspase-8, and caspase-9; remodulation of the Bax:Bcl-2 ratio; and DNA damage." (PMID 34064093, 2021). "In addition, dormant cancer (stem) cells evade NK and T cell-mediated apoptosis through the genetic inactivation of the oncosuppressor caspase 8 (CASP8) and the death receptor Fas cell surface death receptor (FAS)." (PMID 34572009, 2021). "Decreased caspase-8 levels in the serum of women diagnosed with cancer may be related to reduced release of the enzyme from tumor cells due to disturbances in the extrinsic apoptotic pathway." (PMID 33919909, 2021). "It was shown in the human breast cancer cell lines MCF-7 and MDA-MB-435 that SZ-685C compound selectively kills cancer cells via activation of both caspase-8- and caspase-9-based apoptotic pathways by suppressed whole or at least part of the Akt phosphorylation." (PMID 34440090, 2021). "But another study, using same method on a different cohort from South India, reported that 8% of cancer patients had somatic mutations at CASP8 but none of the oral sub mucous fibrosis samples (one of the oral precancers) showed mutation." (PMID 32492030, 2020).
cancer (continued). "Since CASP8 is known to regulate necroptosis and necroptosis can be induced by radiation in a variety of cancers, we aimed to understand whether necroptosis can be exploited to radiosensitize CASP8-mutant HNSCCs to radiation." (PMID 33108350, 2020). "This can possibly be achieved by creating cancer cells that are simultaneously deficient in major molecules that facilitate other RCD pathways over necroptosis (e.g., caspase-8) and proficient in expressing necroptosis-sensitising proteins (e.g., SMAC overexpression)." (PMID 32752206, 2020). "Furthermore, crocin significantly induces apoptosis through activation of caspase-8, up-regulation of Bax, and disruption of mitochondrial membrane potential in this cancer cell line." (PMID 32405344, 2020). "In addition, knockdown of Caspase-8 (CASP8) expression in human RA-sensitive cancer cell lines, SK-N-SH and HL60, clearly enhanced RA signaling and RA-induced differentiation into neural cells expressing TUJ1 and monocytes expressing CD11b, respectively." (PMID 31659279, 2020). "Studies have also shown that mutations in CASP-8 namely R417X (C>T), R218Q (G>A), G310D (G>A), G310D (G>A), D200fs (del TATT frameshift deletion at exon 4), E204X (G>T), Q225X (C>T), T258fs (C>T) and L428Q (T>A) affect functions of CASP-8 and these are positively correlated with cancer progression." (PMID 35047986, 2020). "Similar to some studies using other cancer cell lines, our results demonstrate that genistein activated caspase-8, -9 and -3, and induced PARP cleavage in T24 cells, which was associated the inhibition of the IAP family proteins that interfere with proteolytic activity by binding to caspases." (PMID 31438633, 2019). "Despite these data, compelling evidence is lacking to support a direct causal role for Casp8 inactivation in the generation of cancer chromosomal instability." (PMID 30598363, 2019). "In addition, we observed that the pretreatment of cancer cells with quercetin improves extrinsic and intrinsic apoptosis by activating caspase-8 and caspase-9, respectively." (PMID 31528215, 2019). "We hypothesize that subtle tissue-dependent differences could influence survival by modifying the micro-environment of mutant-CASP8 carcinomas." (PMID 30775178, 2019). "Our analyses further suggest that neutrophil numbers and IL33 levels could be potential factors affecting the survival of mutant-CASP8 carcinomas." (PMID 30775178, 2019). "Loss of caspase-8 activity is known to have a major role in activating anoikis, a form of programmed cell death activated by the detachment of epithelial cells from the ECM, in a variety of cancer types." (PMID 29854765, 2018). "In addition, it was reported that caspase-8 stabilization after proteasome inhibition is observed in some cancer cells." (PMID 30322167, 2018). "Moreover, caspase-8-mediated apoptosis has been demonstrated to mediate the therapeutic synergy of Se compounds and chemotherapy treatment in various cancer settings." (PMID 30326581, 2018). "Interestingly, drug-induced endoplasmic reticulum stress can induce apoptosis in cancer cells via death receptor-mediated activation of caspase-8." (PMID 29876007, 2018). "Immunocytochemistry and Western Blot analyses were used to evaluate expression of apoptotic markers caspase-3 and caspase-8 in cancer cells after treating with effective fractions (based on viability of cancer cells) and the results were compared with Sarcophine." (PMID 29881421, 2018). "Apoptosis mediated by caspase-8 was reported in cancer cells treated with glucose deprivation." (PMID 29554103, 2018). "Other possible targets are Bcl-2 family components, regulators of the mitochondrial pathway of apoptosis, and the promoters of caspase 8 hypermethylation in those cancer cells that have its expression suppressed, as described in some hepatocellular carcinoma mouse models." (PMID 30386235, 2018).
cancer (continued). "Modulation of Caspase-8 may therefore contribute to redirect cytoprotective autophagy to cell death in cancer cells that frequently display high autophagic flux and resistance to canonical apoptotic signaling." (PMID 30501030, 2018). "Overall, these observations suggest that some cancer cells may hijack Caspase-8 function which in turn promote cancer progression and resistance to therapy." (PMID 30501030, 2018). "Moreover, the expression of caspase-3 and caspase-8 (as apoptosis markers) was assessed following treatment of cancer cells with extracted chemical fractions and Sarcophine." (PMID 29881421, 2018). "In addition, the present work indicates that the percentages of neurons in the MPs expressing CASP8 decreased in the cancer-affected stomach wall." (PMID 30019295, 2018). "Most cancer cells, for example, delete or switch off the gene for a protein called Caspase-8." (PMID 28594322, 2017). "Based on studies in hepatocytes and cancer cells, we speculate that TNFR1 ligation in NKT cells deficient in NF-κB signalling activates caspase 8 within complex II death-inducing signalling complex." (PMID 29142275, 2017). "In this study, PA could raised the mRNA and protein expressions of caspase-3, caspase-8 and caspase-9, Res raised these effects of Res treatment, this combination done a good cancer cells apoptosis effects." (PMID 28978315, 2017). "In contrast, R27T did not exhibit significant anti-cancer activity in HeLa cells, in which the overexpression of cFLIPS was associated with impaired caspase-8 activity and R27T resistance." (PMID 28086218, 2017). "Firstly, western blotting analysis of apoptosis signaling showed that as compared to single-agent treatments, the combination distinctly amplified caspase-8-caspase-3 cascade in cancer cells in both cell lines, which led to more cleavage of DNA repair enzymes PARP." (PMID 28460471, 2017). "In addition, different OA derivatives induce apoptosis directly mediated by CASP8 in various cancer cells." (PMID 28061770, 2017). "Caspase-8 is a central player in the apoptotic cascade triggered by death receptors stimulation; consistently, its expression or its apoptotic activity are often reduced in cancer." (PMID 28594322, 2017). "To determine whether cFLIPS loss was sufficient to sensitize cancer cells to TRAIL, we performed siRNA-mediated knockdown of cFLIP and demonstrated increased caspase 8 and PARP cleavage after treatment with TRAIL following loss of cFLIP expression." (PMID 29254146, 2017). "Caspase-8 is a key player in extrinsic apoptosis and its activity is often downregulated in cancer." (PMID 28594322, 2017). "They suggested that DR5/FADD/caspase-8 signaling may have an opposite function to the previous reported in regulating cancer metastasis and may depend on the tumor stage." (PMID 27764170, 2016). "Interestingly, cancer tissues being homozygous for the deletion (n = 15), displayed lowest relative caspase 8 mRNA expression, followed by heterozygous samples (n = 23)." (PMID 27507139, 2016). "Given the intense selection pressure present in a tumor's microenvironment, upregulation of pT273 caspase-8 in some tumors may also affect the metastatic propensity of cancer cells." (PMID 27462786, 2016). "Furthermore, there is evidence for biological interactions between FAT1 and Caspase 8, with FAT1 acting as an antagonist of Caspase 8 in a synthetic lethal screen in cancer cell lines." (PMID 27693639, 2016). "Due to the involvement of caspase-8 in extrinsic apoptosis pathway and caspase-9 in intrinsic apoptosis pathway, our results suggested that both extrinsic and intrinsic apoptosis pathway were participated in compound 3c-induced cancer cell death." (PMID 27625151, 2016). "Therefore, if modulation of caspase-8 function via Src inhibition is to be exploited in the treatment of human carcinomas, care must be taken when choosing appropriate pre-clinical model systems to explore new therapeutic agents." (PMID 27109099, 2016).
cancer (continued). "In addition, TRAIL resistance correlates with accelerated degradation of caspase-8 protein in cancer cells." (PMID 25333816, 2015). "Selective COX-2 inhibition may act synergistically with ionizing radiation to inhibit A549 cancer cells through the activation of caspase-8 and caspase-3." (PMID 26011146, 2015). "CASP8 and H19 have been previously associated with WTs, and H19 in particular has been associated with sporadic bilateral disease, whereas RB1, Mir-195 and TSPAN32 aberrations have not previously been identified in WTs, although detected in other cancers." (PMID 25763109, 2015). "However, identification of small molecules that can stabilize the zymogen caspase 8 homodimerization and promote caspase 8 activation has a great potential for use in cancer therapy." (PMID 25962125, 2015). "Also, cancer stem cells would be induced to undergo apoptosis by the TRAIL/DR5/caspase-8 signaling pathway." (PMID 26304927, 2015). "Second, N-6 and TNFα synergistically induced caspase-8 activation and cancer cell apoptosis." (PMID 26156677, 2015). "Because cFLIP is structurally similar to caspase-8 and the expression of cFLIP isoforms is increased in various types of cancer, including MM, cFLIP represents a critical target for therapeutic intervention, namely via inhibiting its transcription and posttranscriptional modifications." (PMID 25886453, 2015). "Thus, we next analyzed the activated caspase-8 levels in co-cultured cancer cells by means of flow cytometry." (PMID 25888191, 2015). "Furthermore, we provide evidence that regulation of PAR-4 through its hydrolysis by caspase-8 during TNFα-induced apoptosis is an essential step for the induction of cell death in some cancer cells." (PMID 24931006, 2014). "As PAR-4 functions as a tumor suppressor in a subset of human cancers and can be cleaved by caspase-8, our findings might aid in explaining some of the controversial functions of caspase-8 in tumorigenesis." (PMID 24931006, 2014). "Interestingly, activation of caspase-2 has been reported to activate caspase-8, and sequential activation of caspase-2 and -8 is essential for saikosaponin A-induced apoptosis in human cancer cells." (PMID 25333266, 2014). "Our current study has complemented some of these findings where tocotrienols especially the delta isoform could induce a more effective apoptotic cell death in A549 and U87MG cancer cells via caspase-8-mediated Bid and Bax activations." (PMID 25480449, 2014). "While artemisinins and paclitaxel each kill cancer cells by inducing apoptosis, the former (artemisinins) are believed to do so through the intrinsic apoptotic pathway involving caspase 3 and −9, whereas paclitaxel exploits the caspase 8 pathway." (PMID 24391728, 2013). "Similarly, cleavage of caspase-8 (cl-Caspase-8) was observed in cancer cells treated with all other extracts except Chromohalobacter salexigens extract (K30)." (PMID 24305113, 2013). "In addition, Rh2-induced Fas activation and its synergism with betulinic acid toward apoptosis of cancer cells through caspase-8 activation made this lipid raft disruptor an adjunct candidate for anti-cancer therapies." (PMID 23889969, 2013). "Overexpression of FLIP in cancer cells blocks activation of caspase-8." (PMID 23573148, 2013).
cancer (continued). "We assumed that the intrinsic apoptosis pathway induced by MBS extract in the treated cancer cells might be provoked via direct upregulation of caspase 9 gene, via the activation of caspase 8 by the extrinsic pathway, or via the upregulation of Bax gene." (PMID 23122182, 2012). "The activity of caspase-3 and caspase-9 is increased in a dose-and time-dependent manner compared with untreated cells in three cancer cells; the activity of caspase-8 linked to the death receptors fails to be increased in CFPAC-1 and BxPC-3 cells." (PMID 22745658, 2012). "TRAIL and artepillin C alone weakly activated caspase-8 in cancer cells." (PMID 22735465, 2012). "However, IGFBP-3-mediated actions can also occur via activation of a newly discovered cell death receptor, which while capable of activating initiator caspase-8 in cancer cells can also mediate anti-inflammatory effects in healthy endothelial cells." (PMID 22792172, 2012). "In our experiment, increasing levels of caspase-8 and -9 activities were detected in squamocin-treated cells, indicating that squamocin activated both intrinsic and extrinsic pathways to apoptosis in cancer cells." (PMID 21299907, 2011). "This regulation might be very important for cancer cells where subtle differences in the amount of caspase-8 regulate life or death of the cells." (PMID 21625644, 2011). "We have shown that enhancement 0.6 or 1.2 nmol/kg (0.3–0.6 mg/kg)of Dox-induced apoptosis by Sch B in cancer cells was associated with the activation of caspase-9 rather than caspase-8." (PMID 22164272, 2011). "However, Caspase 8 is also central to cell death induced by chemotherapeutic agents in a number of cancer cell types." (PMID 21712824, 2011). "Our findings warrant further investigation on the dual role of caspase-8 in cancer development." (PMID 20808443, 2010). "Caspase-8 is an apical protease involved in the “extrinsic” or death receptor-mediated form of cell death and, as such, would seem to be an ideal candidate for silencing or deletion in cancers." (PMID 20967281, 2010). "Inhibition of Egr-1 by a dominant-negative mutant, or siRNA-mediated knockdown, significantly decreased the expression of the caspase-8 inhibitor protein, c-FLIP, especially its short isoform (c-FLIPS) and Egr-1 expression associated with high c-FLIP expression in a number of cancer cell lines." (PMID 20087343, 2010). "However, 5-Aza has proven to be effective in re-establishing caspase-8 expression in cancer cells, restoring their sensitivity to TRAIL-, anti-FAS-, and drug-triggered apoptosis." (PMID 21108789, 2010). "The Cancer Pathway Finder Array analysis identified numerous cancer-associated genes exhibiting substantial over expression in trisomic BG01V APCs relative to diploid H9 APCs, including CDC25A, IGF1, MMP9, FGFR2, BRCA1, CASP8 and TERT1." (PMID 20423517, 2010). "However, death receptor independent caspase-8/-10 activation has been reported in response to several anti-cancer agents including camptothecin, paclitaxel (Taxol) and etoposide." (PMID 19684859, 2009). "Notably, the MYC, E2F2 and CASP8 genes, which are important regulators of the cell cycle and apoptosis and have previously been implicated in HPV-related processes or cancer 31-33, were identified as common trans-interaction sites in both the HiC and 4C datasets." (PMID 40568071, 2025). "Interestingly, some tumors retain high levels of Caspase-8, thereby suggesting that in some specific tumorigenic contexts oncogenic signalings may hijack Caspase-8 function and therefore Caspase-8 expression may turn to be beneficial for cancer cells." (PMID 41053176, 2025). "Based on these reports, the anti-cancer properties of berberine can be regarded by stimulating both endogenous and exogenous apoptosis via increasing the protein expression of pro-apoptotic molecules Bax, Bad, Bak, and activating Caspase-3, Caspase-8 and Caspase-9." (PMID 40490812, 2025).